DSG2 (desmoglein 2)
Diseases named in the same sentence as DSG2 in open-access papers (continued):
Sharing a sentence is not in itself a finding about the gene and the disease.
pyelonephritis (1 paper, 2021). An inflammatory process affecting the kidney. "These in vivo data support a model in which desmoglein-2 on collecting duct epithelium serves as a receptor for UPEC FimH during pyelonephritis in vivo." (PMID 33513212, 2021). "In this study, we detail the importance of type 1 pili in host-pathogen interaction during ascending pyelonephritis and identify desmoglein-2 as the first receptor for FimH on renal tubular epithelium." (PMID 33513212, 2021). "Finally, we observed co-localization of UPEC with Dsg2 in the collecting ducts of mice with ascending pyelonephritis." (PMID 33513212, 2021). "Finally, we hypothesized that if the Dsg2-FimH interaction was important for pyelonephritis, mannosides could be employed therapeutically in our mouse model." (PMID 33513212, 2021). "In infected C3H/HeN mice, type 1-piliated UPEC and Dsg2 were co-localized within collecting ducts, and administration of mannoside FIM1033, a potent small-molecule inhibitor of FimH, significantly attenuated bacterial loads in pyelonephritis." (PMID 33513212, 2021).
renal cell carcinoma (1 paper, 2025). "In contrast, renal cell carcinomas (RCCs) express high levels of CD46 and desmoglein-2 (DSG2), the primary cellular receptors for several subgroup B adenoviruses, most notably Ad35 and Ad3." (PMID 41445946, 2025).
Sepsis (1 paper, 2016). Sepsis is defined as life-threatening organ dysfunction caused by a dysregulated host response to infection. "The mRNA-levels of different cell adhesion proteins were all numerically upregulated during sepsis, with a significant peak in claudin-1, desmoglein-2 and E-cadherin mRNA levels." (PMID 27044016, 2016).
Stroke (1 paper, 2020). Sudden impairment of blood flow to a part of the brain due to occlusion or rupture of an artery to the brain. "In the present study WES was performed in three patients with family histories of stroke, and it identified a heterozygous variant in MTHFR or in DSG2 in each patient." (PMID 31948402, 2020).
thyroid (1 paper, 2020). "Therefore, four genetic variants associated with thyroid phenotypes are also associated with nine secreted protein abundances, including the apoptosis regulator Desmoglein-2 in blood." (PMID 32182948, 2020). "However, four genetic variants associated with thyroid phenotypes published in the GWAS catalog (rs3761959, rs7528684, rs505922, and rs3184504) were also associated in cis and trans with nine circulating protein abundances (BGAT, CHSTB, DC-SIGN, Desmoglein-2, DYR, FCRL3, GP1BA, MBL, and VCAM-1)." (PMID 32182948, 2020).
type 1 diabetes (1 paper, 2022). "To investigate whether DSG2 supports islet survival, we challenged isolated islets with the cocktail of pro-inflammatory cytokines implicated in the development of type 1 diabetes; namely TNFα, IL-1β, and IFNγ." (PMID 36309486, 2022). "Taken together, our study suggests that DSG2 is an under-appreciated regulator of β-cell function in pancreatic islets and that a better understanding of this adhesion molecule may provide new opportunities to combat type 1 diabetes." (PMID 36309486, 2022).
ulcerative colitis (1 paper, 2019). An inflammatory bowel disease involving the mucosal surface of the large intestine and rectum. "Clinically, shedding of Dsg2 extracellular domains are detected in patients with ulcerative colitis." (PMID 30790141, 2019).
Umbilical hernia (1 paper, 2020). Protrusion of abdominal contents through a defect in the abdominal wall musculature around the umbilicus. "From this set of genes, we highlight KRT14 (Keratin 14), CCBE1, ACAN, Desmoglein 2 (DSG2) and EPYC, which were more enriched in the anatomic development process in the gene network and were upregulated in animals affected by umbilical hernia." (PMID 32379844, 2020).
tumor (81 papers, 2008 to 2026). "DSG2 knockdown suppressed IL-4 and GM-CSF expression, which promoted the enrichment of tumour-associated macrophages to establish a supportive PCSC niche." (PMID 40615400, 2025). "We showed that loss of DSG2 in AsPC-1 cells leads to reduced cell–cell adhesion, smaller cell clusters and a lower tumor cell deposition in perfused livers." (PMID 39107343, 2024). "Here, perfusion with DSG2-deficient AsPC-1 cells led to a reduced number of tumor cells attached to liver tissue compared to AsPC-1 control cells." (PMID 39107343, 2024). "For example, in a variety of cancers, increased expression of desmoglein-2 has been shown to be associated with increased tumor grade 37-41." (PMID 35928727, 2022). "p38 inhibited cSCC-associated long intergenic non-coding RNA (linc-PICSAR) and Dsg2 involved in EV-mediated tumor invasion and drug resistance served as prognostic and therapeutic predictors." (PMID 36291882, 2022). "While we did not observe a difference in VEGFA levels between the DSG2‐high and DSG2‐low patients in the non‐MS cohort, other genes associated with tumour vascularization (e.g. SOX4 and SOX2) were co‐expressed with DSG2." (PMID 34245117, 2022). "According to qRT-PCR and TCGA, high DSG2 expression was positively associated with tumor size (p = 0.027, p = 0.001), lymph node metastasis (p = 0.014, p < 0.001) and TNM stage (p = 0.023, p < 0.001)." (PMID 32095325, 2020). "Loss of Dsg2 in colonic epithelial carcinoma cells results in decreased proliferation and suppresses xenograft tumor growth in mice." (PMID 26918609, 2016). "In most solid tumors derived from epithelial tissues, nests of malignant tumor cells are linked through junction proteins such as E-cadherin, claudins, and desmoglein 2 (DSG2)." (PMID 23898462, 2013). "Genes associated with tumor proliferation such as DSG2 and SPRR3 and genes related to energy metabolism process decreased along the invasion trajectory of the tumor, while the function of tumor progression-related gene BGN and metastasis growth-related gene POSTN gradually increased." (PMID 35899203, 2022). "Furthermore, we recently reported that ectopic expression of Dsg2 in the superficial epidermis renders mice more susceptible to tumor development." (PMID 25871385, 2015). "Therefore, the potential for DSG2 to act as a prognostic biomarker is context dependent and influenced by factors such as organ/tissue type, cancer cell location within a tissue, genetic mutations, as well as the broader tumor microenvironment." (PMID 38188287, 2023). "However, in diffuse-type gastric cancers, decreased expression of Dsg2 is associated with poor prognosis suggesting that Dsg2 may have dual roles as an oncogene and a tumor-suppressor gene." (PMID 26918609, 2016). "We recently showed that Dsg2 associates with caveolin-1 providing a mechanism for regulating mitogenic signaling and modulating the cell surface presentation, both of which may contribute to malignant transformation and tumor progression." (PMID 25785582, 2015). "Spatial mapping revealed preferential enrichment of DSG2+CSCs at tumor margins, where they co-localized with FAP+myofibroblasts (myCAFs)." (PMID 41691490, 2026). "Our results revealed significantly lower tumour-initiating capacity in the DSG2 knockdown group than in the control group." (PMID 40615400, 2025). "Numerous studies have shown that DSG2 is overexpressed in various tumours, including cervical, anaplastic thyroid, colon and gastric cancers." (PMID 40615400, 2025). "Concurrently, to further confirm the contributions of DSG2 to gemcitabine therapy in vivo, we established a tumour xenograft mouse model with PANC02 cells." (PMID 40615400, 2025).
tumor (continued). "It is possible that HIF-1α flexibly regulates adhesion proteins such as DSG2 at different stages of tumor metastasis." (PMID 41381723, 2025). "We discovered that hirudin inhibits tumor cell clustering by impairing DSG2-mediated desmosome through binding to HIF-1α, although the specific binding site remains unvalidated." (PMID 41381723, 2025). "To explore the potential role of the DSG2‐mediated “don't eat me” signal in other tumor types, we analyzed the expression profile of DSG2 in various tumor samples in TCGA and GTEx databases." (PMID 39813162, 2025). "Concurrently, we established a tumour xenograft nude mouse model to further confirm the role of DSG2 in vivo." (PMID 40615400, 2025). "As tumor cells exit hypoxic conditions and undergo reoxygenation, DSG2 expression is reinstated, enabling them to successfully colonize distant organs." (PMID 40507913, 2025). "Another key player, DSG2, a transmembrane protein, modulates tumor invasion and metastasis by regulating intercellular adhesion, thus, affecting tumor malignancy and prognosis." (PMID 40141028, 2025). "In hypoxic tumor regions, DSG2 is downregulated, which triggers EMT-related gene expression changes in primary tumors." (PMID 40507913, 2025). "Once in the bloodstream, cells release from hypoxic stress, leading to a reduction of HIF-1α levels and restoration of DSG2 expression, which promotes tumor cell clustering." (PMID 41381723, 2025). "Decreased expression of DSG2 enables tumor cells to undergo epithelial-mesenchymal transition, whereas upregulation of DSG2 promotes the formation of circulating tumor cells." (PMID 38798352, 2024). "Another notable interaction was the interaction between DSC2 and DSG2 in tumor cells, where the former is one of the 12 TNBC markers we identified." (PMID 38539508, 2024). "Another key finding of our study was the interaction between the DSC2 and DSG2 genes among TNBC tumor cells, suggesting that they are more tightly aggregated with each other than those of other subtypes, including normal epithelial cells." (PMID 38539508, 2024). "This suggests that the increased attachment rate of DSG2 expressing tumor cells is independent from the hepatic expression of the classical binding partners Dsg2 or Dsc2." (PMID 39107343, 2024). "Modifications to Ad5, such as expressing an epithelial junction opener, enhance its anti-tumor effect by increasing its affinity to desmoglein 2 (DSG2), a protein over-expressed in epithelial cancers, thereby improving virus penetration." (PMID 39684701, 2024). "Here, previous data of our group indicate a contribution of the desmosomal adhesion molecule DSG2, the main isoform expressed in pancreatic epithelial cells, to tumor cell migration and invasion of pancreatic carcinoma cells." (PMID 39107343, 2024). "Through the release of EVs, Dsg2 also promoted tumor proliferation in both cutaneous and head and neck SCCs." (PMID 38473864, 2024). "This leads to the inference that the mechanisms through which DSG2 influences cancer progression are influenced by the tumor microenvironment and the origin of the cancer itself." (PMID 38188287, 2023). "Interplay between DSG2 and hypoxia controls metastasis: DSG2 expression promotes metastatic colonization and tumor growth." (PMID 38188287, 2023). "There is increasing evidence from us and others that DSG2 regulates many cancer cell functions, including cell adhesion, proliferation, migration, invasion, vasculogenic mimicry and tumor growth." (PMID 38188287, 2023). "For example, during the adenovirus type 3 (Ad3) infection of epithelial tumor cells, the fiber interacts with junction protein DSG2 to trigger the transient opening of intercellular junctions." (PMID 36016457, 2022). "The basis for preferential tumor transduction is differences in level and accessibility of the target receptor DSG2." (PMID 36360292, 2022). "We hope that DSG2 can serve as a complement to specific tumor-markers for the diagnosis of ESCC and EJA, such as CEA." (PMID 35521959, 2022).
tumor (continued). "DSG2-positve tumor nests contained epithelial junctions marked by claudin 7 and were surrounded by mouse-derived stoma cells and extracellular matrix proteins such as laminin." (PMID 36360292, 2022). "Here, we investigated the role of the fiber shaft in Ad5/3 tumor transduction in vitro and in human DSG2-transgenic mice carrying human DSG2high tumors." (PMID 36360292, 2022). "JO4 action is tumor-specific because DSG2 in normally polarized epithelial tissues is trapped in lateral junctions and not accessible to JO4." (PMID 35562182, 2022). "A central resistance mechanism is the maintenance of desmoglein-2 (DSG2) positive tight junctions between malignant cells that prevents drug penetration into the tumor." (PMID 35562182, 2022). "Our study aimed at producing high-DSG2-affinity viral vectors to improve cell uptake and tumor penetration depth." (PMID 36016457, 2022). "The transduction was first evaluated in a panel of tumor cell lines with DSG2 levels ranging from zero to one hundred percent receptor-positive cells." (PMID 36016457, 2022). "JO4 triggers junction opening in hDSG2-expressing epithelial mouse tumor cells indicating that hDSG2 interacts with mouse signaling and cytoskeletal proteins thus overriding a potential function of mouse DSG2 in the maintenance of junctions in transgenic mice." (PMID 35562182, 2022). "Among 30 GBC patient tissues with low expression of Dsg2, 70% (21 cases) of Dsg2-low tumor specimens showed cSrc activation." (PMID 32989241, 2021). "These properties, such as the scaffolding protein role of Dsg2, inhibit tumor progression by sustaining the inactivated form of Src kinase." (PMID 32989241, 2021). "In this study, we investigated the pathophysiological roles of Dsg2 and found that it functions as a tumor-suppressor protein in GBC." (PMID 32989241, 2021). "Next, we assessed Src activation in tumor specimens from GBC patients with low or high expression of Dsg2." (PMID 32989241, 2021). "To examine the clinical correlation between Dsg2 expression and the growth and progression of GBC, we examined Dsg2 expression in clinical tumor specimens from 67 patients by immunohistochemical staining." (PMID 32989241, 2021). "In the xenograft model, DSG2 promoted tumor growth and reduced this effect considerably with overexpression of non-palmitoylated DSG2 in cells." (PMID 34203070, 2021). "Using clinicopathological analyses of GBC patients along with molecular in vitro and tumor in vivo analysis of GBC cells, we showed that reduction of Dsg2 expression was highly associated with higher T stage, more perineural, and lymphatic invasion." (PMID 32989241, 2021). "Second, in SCC, upregulated DSG2 promotes tumor growth by down-regulating miR-146a, resulting in increased expression of Interleukin 8 (IL-8) and release in EVs." (PMID 34203070, 2021). "The upregulation of DSG1 and/or DSG2 is related to enhanced tumour progression and/or shorter patient survival." (PMID 32850288, 2020). "Tumor types with upregulated DSG-2 would be prime subjects for oncolytic therapy with species B Ads binding to DSG-2, like HAdV-B3 and HAdV-B7." (PMID 32957644, 2020). "DSG2 is a biomarker that promotes tumor proliferation and metastasis and is correlated with poor prognosis in early-stage CC." (PMID 32514251, 2020). "The expression of the DSG1 and DSG2 proteins was significantly lower in EHCC tumour tissues than in normal biliary tract tissues, biliary tract adenoma, and peritumoral tissues (P < 0.05)." (PMID 32850288, 2020). "In conclusion, DSG2 was a novel tumor promoter in CC, and probably promoted cancer development by promoting the occurrence of PLNM." (PMID 32514251, 2020). "Univariate analysis showed that DSG2 expression (P < 0.001), tumor size (P = 0.029), LVSI (P = 0.008) and PLNM (P < 0.001) were prognostic factors for overall survival (OS)." (PMID 32514251, 2020). "DSG2 has different functions in various cancers and can act as either an oncogene or a tumour suppressor." (PMID 32300605, 2020).
tumor (continued). "High DSG2 expression was significantly correlated with several poor clinicopathological features, including tumor size (P = 0.022), PLNM (P < 0.001), recurrence (P < 0.001) and vital status in 5 years (P < 0.001)." (PMID 32514251, 2020). "The expression level of DSG2 in patients with early TNM tumor stage (I–II) was lower than patients with advanced TNM stage (III–IV) (0.063 ± 0.040 vs 0.128 ± 0.098, p = 0.023)." (PMID 32095325, 2020). "DSG2, as a desmosomal cadherin, is abnormally expressed in various tumor tissues, and is mainly involved in regulating the proliferation, metastasis, tumor microenvironment, and tumor VM of tumor cells." (PMID 32997416, 2020). "Immunohistochemistry staining analysis showed higher expression of DSG2 in LUAD tissues compared with the adjacent non-tumor tissues (p < 0.001)." (PMID 32095325, 2020). "A decrease in desmoglein-2 expression level can serve as an important sign of increased epithelial-to-mesenchymal transition and, accordingly, increased tumor aggressiveness during the transition from 2D to 3D state." (PMID 33291824, 2020). "On the contrary, overall downregulation of DSG-2 in tumor cells would prevent initial infection and render oncolytic Ad therapy inefficacious." (PMID 32957644, 2020). "From the evidence provided in this review, we believe that Ads other than HAdV-C5, that target for instance CD46 or DSG-2, would be most suitable for the targeting and killing of the majority of tumor types." (PMID 32957644, 2020). "Although the expression of DSG1 and DSG2 has been proven to be involved in the progression and prognosis of certain types of tumours, the expression and significance of DSG1 and DSG2 in EHCC have not been previously reported." (PMID 32850288, 2020). "We observed that the expression of DSG1 and DSG2 in EHCC tumour tissues presented a significant downregulation compared to the nontumour tissues." (PMID 32850288, 2020). "A putative role of DSG2 as a tumor suppressor in human breast cancer has been suggested, and its expression is related to the tumor size, lymph node metastasis, and stage in lung adenocarcinoma." (PMID 32498335, 2020). "The JOC-DOTA (Eu) chelates were able to bind DSG2 and inhibit virus in vitro suggesting they will bind to tumor cells in vivo and the metal chelate can be used to irradiate or mark the tumor for in vivo imaging." (PMID 30992466, 2019). "We have described a new approach to exposing tumors to the action of the immune system and oncological therapy using designer proteins that bind to DSG2 and open tumor tight junctions." (PMID 30992466, 2019). "Desmoglein 2 (DSG2) acts as an oncogene by accelerating tumor growth of non-small-cell lung carcinoma (NSCLC)." (PMID 29855376, 2018). "Work has been performed to increase the affinity of Ad3 fiber-knob for DSG2 in pursuit of a therapeutic molecule capable of loosening epithelial cell junctions to improve tumour penetration culminating in the JO-4 molecule." (PMID 29904022, 2018). "Desmocollin-2 (DSC2) and DSG2, two transmembrane cell adhesion proteins of desmosomes, were reported with opposite functions in tumor progression." (PMID 27107420, 2016). "We and others have shown that Dsg2 promotes keratinocytes proliferation and tumor development by activation of mitogenic signaling pathways." (PMID 25871385, 2015). "We recently showed that overexpression of Dsg2 under the control of the involucrin promoter in the skin of transgenic mice (Inv-Dsg2) resulted in hyperplasia of the epidermis and enhanced sensitivity to tumor induction." (PMID 25785582, 2015). "The role of Dsg2 in cancers is equally controversial and the expression level is dependent on the tumor type." (PMID 25785582, 2015). "DMBA/TPA-induced BCCs in Inv-Dsg2/Ptc1+/lacZ mice exhibit classical activation of the Hh pathway; whereas, squamous-derived neoplasia lack detectable Hh activity." (PMID 25871385, 2015).